RNU6-501P (RNA, U6 small nuclear 501, pseudogene)
Gene: Small nuclear RNA gene on chromosome 1 (201,733,406 to 201,733,505, forward strand). Ensembl gene ENSG00000200942.
Homologues: Orthologues: chimpanzee U6 (100% identical), macaque U6 (94% identical), mouse Gm24927 (89% identical), mouse Gm22509 (87% identical), guinea pig U6 (81% identical), pig U6 (81% identical). Paralogues in human: RNU6-11P (92% identical), RNU6-37P (92% identical), RNU6-12P (91% identical), RNU6-13P (91% identical), RNU6-16P (91% identical), RNU6-32P (91% identical), RNU6-45P (91% identical), RNU6-1 (90% identical), RNU6-1131P (90% identical), RNU6-17P (90% identical), RNU6-18P (90% identical), RNU6-2 (90% identical), and 1283 more.